IL33 (interleukin 33)
Diseases named in the same sentence as IL33 in open-access papers (continued):
Sharing a sentence is not in itself a finding about the gene and the disease.
Pleural effusion (5 papers, 2014 to 2025). The presence of an excessive amount of fluid in the pleural cavity. "This work aimed to determine the diagnostic role of IL-33 in pleural effusions." (PMID 31238901, 2019). "In the BALF of children with SCAP complicated with pleural effusion (PE), the levels of IL-18, the IL-18/IL-38 ratio, and the IL-33 level were significantly elevated (P < 0.05)." (PMID 40352606, 2025). "A recent study showed that the specificity and sensitivity combined pleural effusion IL-33 detection, ADA detection and the peripheral blood T-SPOT test were 100% and 88.5%, respectively." (PMID 36111237, 2022). "In summary, this study compared the AUC, sensitivity and specificity of pleural effusion IL-33, ADA and blood TSPOT for the diagnosis of tuberculous pleurisy." (PMID 34425761, 2021). "The results of this study showed that the level of IL-33 in pleural effusion was significantly higher in patients with tuberculous pleurisy than in non-tuberculous pleural effusion." (PMID 34425761, 2021). "AUC for combined detection of pleural effusion IL-33, ADA and peripheral blood T-SPOT.TB is the largest, with a value of 0.962." (PMID 34425761, 2021). "The level of pleural fluid IL-33 was positively correlated with pleural effusion ADA and peripheral blood T-SPOT.TB." (PMID 34425761, 2021). "Correlation between pleural fluid IL-33, pleural effusion ADA and peripheral blood T-SPOT.TB was analyzed, comparison of the three separate and combined diagnostic efficacy was also performed." (PMID 34425761, 2021). "Combined detection of pleural effusion IL-33, ADA and peripheral blood T-SPOT.TB can improve the diagnostic efficacy of tuberculous pleurisy." (PMID 34425761, 2021). "The level of IL-33 in pleural fluid was both positively linear correlated with pleural effusion ADA and peripheral blood T-SPOT.TB (r = 0.343, 0.450, P < 0.05 respectively)." (PMID 34425761, 2021). "One hundred seventeen patients with pleural effusions of different etiologies had a quantitative measurement of IL-33 by ELISA technique in pleural effusion and serum samples of the patients." (PMID 31238901, 2019). "One hundred seventeen patients with pleural effusions of different etiologies had a quantitative measurement of IL-33 in their pleural effusion and serum samples by ELISA technique." (PMID 31238901, 2019). "The cutoff point of the pleural/ serum IL-33 ratio for the diagnosis of tuberculous ‘pleural effusion was > 1.4; with a sensitivity of 91.7% and specificity of 100%." (PMID 31238901, 2019). "The concentrations of IL-33 in the pleural effusion positively correlated with that of the corresponding serum samples in all patients of the study groups (r = 0.677, P < 0.001)." (PMID 31238901, 2019). "Pleural IL-33 is a novel biomarker for diagnosis and differentiation of different forms of pleural effusion especially tuberculous from malignant effusions." (PMID 31238901, 2019). "IL-33 levels in pleural effusion and serum samples were detected using sandwich enzyme-linked immunosorbent assay in 23 patients with TPE and 21 patients with MPE." (PMID 24959294, 2014). "The present study identified that the level of IL-33 was increased in the pleural effusions and sera of the patients with MPE and TPE." (PMID 24959294, 2014). "The level of IL-33 in pleural effusion and serum samples obtained from patients with MPE and TPE were analyzed." (PMID 24959294, 2014). "The concentration of IL-33 in the pleural effusions was positively correlated with that in the serum samples in the patients with TPE and MPE (r=0.56, P=0.05; and r=0.54, P<0.05)." (PMID 24959294, 2014). "In the present study, the pleural effusion-serum IL-33 gradient and the pleural effusion-serum IL-33 ratio were observed to be significantly increased in the patients with TPE compared with those with MPE." (PMID 24959294, 2014). "The concentration of IL-33 in pleural effusion and serum samples was detected in 23 patients with TPE and 21 patients with MPE." (PMID 24959294, 2014).
Pleural effusion (continued). "The IL-33 concentration in the pleural effusion (22.96±0.98 ng/l) was significantly higher than that in the corresponding concentration of serum (14.27±0.86 ng/l; P<0.01) in the patients with TPE." (PMID 24959294, 2014). "The concentration of IL-33 in the pleural effusions was positively correlated with that in the serum samples in each group (TPE: r=0.563, P=0.05; MPE: r=0.535, P<0.05)." (PMID 24959294, 2014). "This study found that the combined detection of pleural effusion IL-33, ADA and peripheral blood T-SPOT.TB could further improve the sensitivity and specificity of TPE diagnosis." (PMID 34425761, 2021). "Lee and Xuan and other scholars found that the level of IL-33 in pleural effusion of patients with tuberculous pleurisy was significantly higher than other causes of pleural effusion and serum IL-33 levels, the sensitivity was 78% and 86.96%, specificity was 65% and 90.48% respectively." (PMID 34425761, 2021). "The concentrations of IL-33 in the pleural effusions were significantly correlated to that of the serum concentrations in each group (TPE: r = 0.848, P = < 0.001; MPE: r = 0.881, < 0.001) and pleural ADA in patients with tuberculous pleural effusions, (r = 0.38, P < 0.001)." (PMID 31238901, 2019). "IL-33 may serve as a novel biomarker to differentiate pleural effusions, especially tuberculous from malignant effusions." (PMID 31238901, 2019). "IL-33 level may serve as a novel biomarker to differentiate pleural effusions, especially tuberculous from malignant effusions." (PMID 31238901, 2019). "While the cutoff point of the pleural/ serum IL-33 ratio for the diagnosis of tuberculous ‘pleural effusion was > 1.4; therefore patients with pleural/serum IL-33 ratio > 1.4 had a high probability of being diagnosed with tuberculous pleural effusion with 91.7% sensitivity and 100% specificity." (PMID 31238901, 2019). "The concentrations of pleural IL33 in tuberculous, malignant and parapneumonic pleural effusion groups were also positively correlated with their corresponding serum IL33 level (r = 0.848, P < 0.001; r = 0.881, P < 0.001; and r = 0.965, P < 0.001) respectively." (PMID 31238901, 2019). "Neutrophils are activated in various stages of pleural tuberculosis infection, and thus may contribute to the elevated level of IL-33 in pleural effusions." (PMID 24959294, 2014). "Furthermore, the concentration of IL-33 in the pleural effusion (12.60±5.15 ng/l) was significantly lower than that in the corresponding serum concentration (14.20±6.22 ng/l; P<0.05) in the patients with MPE." (PMID 24959294, 2014). "Second, we did not analyze serial IL-33 levels or measure Th2 and Th1 cytokines such as IFN-γ in pleural effusion." (PMID 34425761, 2021).
polyposis (5 papers, 2018 to 2023). "In mice, epithelium-derived CRC cells generate IL-33 during polyposis and that IL-33 activates at least two cell types, subepithelial myofibroblasts and mast cells, to form a tissue microenvironment favorable to polyposis." (PMID 35720302, 2022). "It is quite likely that, in the APC Min/+ model of polyposis, IL-33 promotes polyposis formation via Th2 cytokines IL-4 and IL-13 as well as inflammatory cytokine IL-6, which facilitate mast cell function." (PMID 29499051, 2018). "We observed upregulation of the IL-33/AREG axis in Rbm47-IKO mice, a pathway previously shown to promote polyposis in ApcMin/+ mice." (PMID 37014710, 2023). "Taken together with the current findings showing increased IL-33 and AREG expression in Rbm47-IKO mice, we propose that these adaptations might plausibly protect against intestinal injury and inflammation-associated tumorigenesis while promoting spontaneous polyposis." (PMID 37014710, 2023).
primary biliary cirrhosis (5 papers, 2018 to 2024). "The activation of IL-33/ST2 signaling has also been shown to be positively correlated with the severity of primary biliary cholangitis." (PMID 36271450, 2022). "Likewise, in the field of hepatology, IL-33 has been reported to correlate with liver injury in patients with primary biliary cirrhosis (PBC)." (PMID 30034292, 2018). "Thus, in primary biliary cirrhosis, IL-33 repairs biliary cells, but signaling is carcinogenic." (PMID 32486265, 2020). "Further, Lgals3 ablation enhances liver steatosis, but attenuates inflammation and IL-33 dependant fibrosis in mouse model of non-alcoholic fatty liver disease (NAFLD), and enhances bile duct damage and liver fibrosis in xenobiotic induced primary biliary cholangitis (PBC)." (PMID 30800112, 2019).
retinal degeneration (5 papers, 2019 to 2023). Degeneration of the retina. "IL-33 deficiency enhanced retinal degeneration and gliosis following RD which was related to sustained subretinal inflammation from infiltrating macrophages." (PMID 31796062, 2019). "The authors found that IL-33 was released by Müller cells after light exposure, which then induced CCL2, IL-6 and IL-1β expression through autocrine activation of Müller cells and promoted immune cell infiltration and retinal degeneration." (PMID 31796062, 2019). "It was shown that IL-33 production by Müller cells was able to induce the expression of other chemokines and cytokines, including CCL2, which has been shown to be produced primarily by Müller cells in retinal degenerations to recruit macrophages into the site of damage." (PMID 31379825, 2019).
alcoholic liver diseases (4 papers, 2019 to 2020). A disorder caused by damage to the liver parenchyma due to alcohol consumption. "It is also important that we embark on a large-scale study in the future to evaluate IL-33, as it has been shown to be upregulated in patients suffering from alcoholic liver disease." (PMID 30859103, 2019). "In human patients with alcoholic liver disease, sST2 but not IL-33 was correlated to the severity of the disease." (PMID 31507607, 2019).
aortic valve stenosis (4 papers, 2013 to 2025). Aortic valve stenosis (AVS) is a condition characterized by narrowing of the heart's aortic valve opening. "Valvular interstitial cells were also shown to upregulate endogenous IL-33 expression in vitro upon stimulation as well as in aortic valve stenosis tissue." (PMID 40287595, 2025). "In this study, we investigated the influence of eLDL on IL-6 and IL-33 induction, and also the impact of eLDL on calcification in aortic valve stenosis (AS)." (PMID 37509127, 2023). "Although literature on the role of IL-33 in calcification is scarce, patients suffering from nonrheumatic aortic valve stenosis (with calcified lesions in aortic valves) were shown to have increased plasma IL-33 levels." (PMID 40287595, 2025). "Regarding the cardiac valves, the expression of IL-33 and ST2 has been reported in aortic valves and recently a role of IL-33 in the progression of nonrheumatic aortic valve stenosis has been described via VIC differentiation into myofibroblasts and osteoblasts." (PMID 33669101, 2021).
Atrophic Gastritis (4 papers, 2015 to 2024). "In saline-treated mice there was obvious intrinsic factor staining of chief cells at the base of the gland, however, this staining was lost after IL33 treatment, reinforcing the observation that systemic administration of IL33 can cause gastric atrophy." (PMID 28210674, 2015). "In extensive atrophic gastritis, the expression of CCL2 and CCL19 was correlated with the infiltration of central memory CD4 T cell, and CD56dim natural killer cell was associated with IL33 expression." (PMID 33426088, 2020).
Cerebral ischemia (4 papers, 2022 to 2025). Restriction of arterial blood supply to the brain associated with insufficient oxygenation to support the metabolic requirements of the tissue. "Following cerebral ischemia, damaged microglia release IL‐33, a potent chemokine that enhances neuronal survival and preserves white matter integrity through the IL‐33/ST2 signaling pathway." (PMID 41367136, 2025). "For the therapeutic potential of IL-33, we found that single dose on day 3 after cerebral ischemia could significantly improve the BBB function and neurological recovery." (PMID 37968698, 2023). "In addition, approximately 50% of the brain infiltrating Tregs express ST2 and expand in response to IL-33 after brain ischemia." (PMID 35432343, 2022). "Furthermore, a previous study highlighted that IL‐33 could ameliorate cerebral ischemia in the MCAO model by suppressing the Th17 response." (PMID 37143406, 2023). "Therefore, we hypothesized that GTA could promote lipogenesis in astrocytes and improve BBB repair after cerebral ischemia, and FASN mediated IL-33 upregulation might be involved." (PMID 37968698, 2023).
cerebrovascular diseases (4 papers, 2013 to 2022). "Several studies have demonstrated the gene variation of IL33 is associated with some cardiovascular and cerebrovascular diseases." (PMID 24107076, 2013). "The low sample size of such studies indicate it would be premature to suggest a different role for IL-33 in cerebrovascular disease compared to other cardiovascular diseases." (PMID 34723980, 2021). "A possible explanation might be found in studies that tried to demonstrate the role of interleukin-33 (IL-33), i.e., the main ligand for ST2, on cerebrovascular diseases." (PMID 35683529, 2022).
chronic spontaneous urticaria (4 papers, 2017 to 2024). "This study focused on the role of interleukin 33 (IL-33) and its polymorphisms, particularly SNP rs1929992, in chronic spontaneous urticaria (CSU)." (PMID 39769469, 2024). "Chronic spontaneous urticaria is characterized by increased levels of IL-25, IL-33, and TSLP, indicating the possible involvement of ILC2s." (PMID 38474426, 2024). "IL-25 and IL-33 can modulate many aspects of mast cell function, including proliferation and production of a variety of Th2 cytokines in chronic spontaneous urticaria." (PMID 35874756, 2022). "In addition, increased expression of IL-25 and IL-33 on mast cells was observed in lesional skin of patients with chronic spontaneous urticaria." (PMID 35874756, 2022).
dementia (4 papers, 2020 to 2024). Loss of intellectual abilities interfering with an individual's social and occupational functions. "Notably, IL-33 significantly down-modulated NF-kB nuclear translocation in cells of HC alone, indicating this as possible mechanisms by which IL-33 favors the maintenance of an anti-inflammatory milieu in individuals in whom dementia is not present." (PMID 32505187, 2020).
diabetic retinopathy (4 papers, 2022 to 2025). "These molecules are expressed in different eye diseases, and diabetic retinopathy; the predominant DAMPs are S100, HMGB1, uric acid, HSPs, ATP, cyclophilin A, Aβ, IL 1-α, IL-33, nuclear DNA, mtROS, formyl peptide, and lipid from the mitochondrial membrane." (PMID 36678750, 2022).
dysplasia (4 papers, 2022 to 2025). A usually neoplastic transformation of the cell, associated with altered architectural tissue patterns. "Comparing the highest versus lowest category of each immune‐related protein, eight proteins were inversely associated with dysplasia with sex‐ and age‐adjusted ORs ranging from 0.30 (95%CI: 0.12–0.77) for IL‐33 to 0.76 (95%CI: 0.59–0.99) for MIP‐1B." (PMID 39482824, 2025). "Eight of the 33 immune‐related markers (IL‐33, BCA‐1, GRO, CCL19 (MIP‐3B), sTNFRII, CXCL6 (GCP2), CRP and MIP‐1B) were inversely associated with dysplasia, with univariate ORs ranging from 0.30 (95%CI: 0.12–0.77) for IL‐33 to 0.76 (95%CI: 0.59–0.99) for MIP‐1B." (PMID 39482824, 2025). "In Liu’s study, they report that the expression level of IL-33 is increased from low-grade to high-grade dysplasia to EAC, suggesting a gradual activation of IL-33 during the transformation of a premalignant lesion to EAC." (PMID 40520454, 2025). "Using this model, we successfully created a gradually progressing pathological stage containing normal, low-grade dysplasia, high-grade dysplasia, and EAC, which provided a good model for reflecting the alteration of IL-33 in this process." (PMID 36110250, 2022). "We found that patients with dysplasia had lower levels of IL‐33, BCA‐1, GRO, CCL19 (MIP‐3B), sTNFRII, CXCL6 (GCP2), CRP and MIP‐1B compared to gallstones patients without dysplasia." (PMID 39482824, 2025).
esophageal cancer (4 papers, 2023 to 2025). A primary or metastatic malignant neoplasm involving the esophagus. "In addition, increased expression of IL-33 is associated with poor survival in esophageal cancer patients." (PMID 37543673, 2023). "Regarding the therapeutic potential of targeting the IL-33/ST2 signal in esophageal cancers (both EAC and ESCC), information is extremely limited so far." (PMID 40520454, 2025). "There is a small amount of evidence describing the role of IL-33 in other gastrointestinal tract cancers, such as esophageal cancer." (PMID 37296602, 2023). "Currently, there are several studies describing the role of IL-33 in esophageal cancers." (PMID 40520454, 2025). "For different types of esophageal cancers, the role of IL-33/ST2 may also be different." (PMID 40520454, 2025). "Collectively, current evidence suggests that an activated IL-33/ST2 axis might have a potential effect on the development of esophageal inflammation in EoE, GERD, and esophageal cancer by multiple mechanisms." (PMID 40520454, 2025).
falciparum malaria (4 papers, 2015 to 2024). "In post-mortem studies of falciparum malaria, accumulation of monocytes in pulmonary vessels suggest a contribution to ALI that may occur in tandem with neutrophils through IL-33-mediated pathways." (PMID 39150978, 2024). "IL-33 serum levels are significantly higher in children with severe Plasmodium falciparum malaria than children without complications or noninfected children." (PMID 36362246, 2022).
head and neck cancer (4 papers, 2018 to 2024). A primary or metastatic malignant neoplasm affecting the head and neck. "Moreover, IL-33 secreted by CAFs from patients with head and neck cancer has been associated with invasion by activating Epithelial to Mesenchymal Transition (EMT), which emphasize the importance of studying IL-33 in metastasis." (PMID 31281317, 2019). "In CRC, the activation of EMT and the formation of TB could be exerted by CAFs (desmoplastic reaction) by activating the IL-33/ST2 axis, as was observed in head and neck cancer cell lines, favoring metastasis to LNs." (PMID 31281317, 2019).
hepatic granuloma (4 papers, 2016 to 2023). A granuloma located in the liver. "Selective ablation of IL-33 with a consequent diminution of inflammatory response in the liver may represent a potential therapeutic approach to hepatic granuloma pathology caused by S. japonicum." (PMID 27445267, 2016). "In order to analyse how the IL-33/ST2 pathway affects the formation of hepatic granulomas, we evaluated haematoxylin-eosin (HE) liver slides." (PMID 37373379, 2023). "During Schistosoma japonicum infection, IL-33 participated in hepatic granuloma pathology; in the liver of Leishmania donovani-infected mice, the IL-33/ST2 axis suppressed Th1 response, and patients with visceral leishmaniasis exhibited higher serum IL-33 levels." (PMID 29180837, 2017). "IL-33 and its receptor ST2 are involved in Th2-biased immune responses through the release of IL-5 and IL-13 and subsequent hepatic granuloma pathology induced by Sj infection." (PMID 31200771, 2019). "Recently, it has been shown that IL-33 and ST2 are involved in Th2-biased immune responses by triggering on the one hand IL-5 and IL-13 release and on the other hand hepatic granuloma pathology induced by Sj infection." (PMID 31200771, 2019). "Herein, we investigated the role of IL-33 and its receptor ST2L in hepatic granuloma pathology induced by Schistosoma japonicum infection." (PMID 27445267, 2016).